PGLYRP1 (peptidoglycan recognition protein 1)
Diseases named in the same sentence as PGLYRP1 in open-access papers (continued):
Sharing a sentence is not in itself a finding about the gene and the disease.
Lyme disease (2 papers, 2020 to 2024). Lyme disease (named after the towns in the USA where the disease was first identified) is a bacterial infection caused by Borrelia burgdorferi. "We validated the interaction of PGLYRP1 with Borrelia and were able to use PGLYRP1-deficient mice as a model to understand the role of this protein in Lyme disease pathogenesis." (PMID 33175909, 2020). "To assess the role of PGLYRP1 in the pathogenesis of Lyme borreliosis, we compared the outcomes of B. burgdorferi infection of BALB/c WT and PGLYRP1-/- mice." (PMID 33175909, 2020). "Notably, PGLYRP-1 plays a role in Lyme disease and immune dysregulation." (PMID 39483916, 2024).
melanoma (2 papers, 2024 to 2025). A malignant, usually aggressive tumor composed of atypical, neoplastic melanocytes. "Notably, CXCL6 exhibited strong negative correlations with B and T cells in primary melanomas, while PGLYRP1 was positively associated with neutrophils and macrophages in metastatic ones." (PMID 40943183, 2025). "PGLYRP1 correlated positively with B cells in the metastatic melanomas, but not in the primary ones." (PMID 40943183, 2025).
Obesity (2 papers, 2022 to 2026). Accumulation of substantial excess body fat. "Confirming the differences in innate immunity between the two cell types in response to obesity, we observed that Pglyrp1 was upregulated in the epithelia and downregulated in the stroma." (PMID 36424602, 2022).
pneumonia (2 papers, 2019 to 2022). An acute, acute and chronic, or chronic inflammation focally or diffusely affecting the lung parenchyma, caused by an infection in one or both of the lungs (by bacteria, viruses, fungi, or mycoplasma.). "Peptidoglycan recognition protein 1 (PGLYRP1) is another of these eight DEPs and was found for the first time to be up‐regulated in patients with KD compared to normal control and pneumonia in our study." (PMID 30761252, 2019). "Moreover, the expression of eight DEPs (PECAM1, PGLYRP1, AHCY, BHMT, EML3, ICOSLG, IGHV3‐23 and RTN4RL2) in normal and pneumonia groups (two patients) was quite different from that in the KD group." (PMID 30761252, 2019). "Moreover, the expression of eight of these 30 DEPs (PECAM1, PGLYRP1, AHCY, BHMT, EML3, ICOSLG, IGHV3‐23 and RTN4RL2) clustered normal and pneumonia samples into one group and clustered KD samples into another group, which heightens the importance of these eight DEPs in KD." (PMID 30761252, 2019).
allergic asthma (1 paper, 2016). A asthma with a basis in a pathological type I hypersensitivity reaction. "PGLYRP1 is an antimicrobial innate immunity protein commonly implicated in allergic asthma." (PMID 27247105, 2016).
Autoimmunity (1 paper, 2026). The occurrence of an immune reaction against the organism's own cells or tissues. "Pglyrp1-deficient myeloid cells showed abnormalities in antigen presentation and T-cell activation, indicating that PGLYRP1 acts as a pro-inflammatory molecule in myeloid cells during autoimmunity." (PMID 41487016, 2026).
breast carcinoma (1 paper, 2024). "Higher circulating levels of PGLYRP1, CAMP, MMP9 and CEACAM8 prior to and after the first dose of DOX chemotherapy may further contribute to progressive cardiovascular disorders in breast cancer survivors and may potentially predict the risk of both acute subclinical and late cardiotoxicity." (PMID 39273682, 2024). "In this study we analyzed peripheral blood samples from 40 patients with early-stage breast cancer treated with DOX-based chemotherapy for protein and mRNA expression of PGLYRP1, CAMP, MMP9 and CEACAM8." (PMID 39273682, 2024). "The aim of this study was to validate previously determined mRNA biomarkers of DOX-induced presymptomatic cardiotoxicity, PGLYRP1, CAMP, MMP9, and CEACAM8 and to assay their protein expression in breast cancer patients’ circulation." (PMID 39273682, 2024). "In this study, we evaluated the potential of the neutrophil biomarkers PGLYRP1/TAG7, CAMP/LL37, MMP9, and CEACAM8/CD66b to predict DOX-induced cardiotoxicity in patients with early-stage breast cancer." (PMID 39273682, 2024). "Here, we report that DOX therapy induced increased circulating levels of the neutrophil markers PGLYRP1, CAMP, MMP9, and CEACAM8 early after a single dose of chemotherapy in breast cancer patients." (PMID 39273682, 2024). "This study aimed to validate mRNA expression of the previously identified biomarkers of DOX-induced cardiotoxicity, PGLYRP1, CAMP, MMP9, and CEACAM8, and to assay their protein expression in the peripheral blood of breast cancer patients." (PMID 39273682, 2024).
carditis (1 paper, 2020). "In our study, PGLYRP1 deficiency in BALB/c mice did not result in differences in carditis and tenosynovitis severity, despite a higher pathogen load." (PMID 33175909, 2020).
coronary artery calcification (1 paper, 2009). Calcification of the coronary artery, used as a measure of coronary atherosclerosis, a risk factor for myocardial infarction. "The role of innate immunity in atherogenesis is less well established; PGLYRP1 participates in recognition of bacteria by neutrophils, but is independently associated with coronary artery calcification and abdominal aortic plaque." (PMID 20034393, 2009).
endometriosis (1 paper, 2017). The growth of functional endometrial tissue in anatomic sites outside the uterine body. "In CM of patients with endometriosis we reported the differential expression of Peptidoglycan recognition protein 1 (Pglyrp1)." (PMID 28174513, 2017). "Nine proteins were quantitatively reduced in endometriosis, including some proteins related with local innate immunity (CRISP-3 and Pglyrp1) and protection against oxidative stress (HSPB1)." (PMID 28174513, 2017). "The absence of Pglyrp1 might represent a molecular mechanism involved in the higher prevalence of infections in patients with endometriosis." (PMID 28174513, 2017).
experimental autoimmune encephalomyelitis (1 paper, 2024). An autoimmune demyelinating disease of the central nervous system that is produced experimentally in animals by the injection of homogenized brain or spinal cord in Freund's adjuvant. "PGLYRP-1 deficient mice were also protected from experimental autoimmune encephalomyelitis (EAE) with defects in antigen presentation and alterations in expression profiles of myeloid cells." (PMID 39483916, 2024).
gastric cancer (1 paper, 2021). A primary or metastatic malignant neoplasm involving the stomach. "Five genes, e.g., DGAT2, JAKMIP1, KRT7, PGLYRP1, and TINAGL1, showed very low correlation coefficient and/or insignificant p-values, suggesting they might not be regulated by KLF5 in human gastric cancer." (PMID 33923166, 2021).
heart failure (1 paper, 2024). Inability of the heart to pump blood at an adequate rate to meet tissue metabolic requirements. "Signs of heart failure and LVEF decrease to <40% was recorded in 4 patients with elevated mRNA and protein expression of PGLYRP1, CAMP, MMP9 and CEACAM8 at baseline and after the initial chemotherapy dose." (PMID 39273682, 2024).
hypothyroidism (1 paper, 2023). Abnormally low levels of thyroid hormone. "In contrast to the conventional drug L-thyroxine for curing hypothyroidism, YJT has a unique efficacy for attenuating systematic inflammatory responses via the suppression of intestinal LPS–TLR4 and peptidoglycan–Nod2/Pglyrp1 signaling pathways." (PMID 37270649, 2023).
inflammatory bowel disease (1 paper, 2024). A spectrum of small and large bowel inflammatory diseases of unknown etiology. "Unraveling the role of the PGLYRP-1-based PGN recognition system in inflammatory bowel diseases will be important in the context of diseases associated with NOD2 and GEF-H1 variants." (PMID 39483916, 2024). "We next investigated whether the PGLYRP-1 dependent gene signature induced by was detectable in inflammatory bowel disease." (PMID 39483916, 2024).
influenza (1 paper, 2021). An acute viral infection of the respiratory tract, occurring in isolated cases, in epidemics, or in pandemics; it is caused by serologically different strains of viruses (influenzaviruses) designated A, B, and C, has a 3-day incubation period, and usually lasts for 3 to 10 days. "In comparison, three patients had high activation of only a subset of influenza-connected genes PRTN3, LTF, PGLYRP1, DEFA1B, DEFA1, DEFA4, ELANE, and MPO." (PMID 34335605, 2021).
liver fibrosis (1 paper, 2024). "In conclusion, Wfdc21, Lcn2, Pglyrp1, and Mmp8 may be potential and novel neutrophil targets to decrease liver fibrosis." (PMID 39040848, 2024).
lung injury (1 paper, 2023). "In addition, certain PGLYRP1-derived peptides have been described to inhibit proinflammatory cytokine-production in a mouse model of acute lung injury with diffuse alveolar damage." (PMID 37293294, 2023).
mucositis (1 paper, 2022). Mucositis is inflammation and damage of the mucous membranes lining the mouth and other parts of the gastrointestinal (GI) tract. "In our mucositis group, a positive correlation was observed between the expression of PGLYRP1 and bleeding on probing in the follow-up." (PMID 35329310, 2022). "Furthermore, there was a strong positive correlation between sTREM-1 and PGLYRP1 in the mucositis group at baseline and after treatment, which is expected once the latter is a functional ligand of the first." (PMID 35329310, 2022).
osteoporosis (1 paper, 2025). A condition of reduced bone mass, with decreased cortical thickness and a decrease in the number and size of the trabeculae of cancellous bone (but normal chemical composition), resulting in increased fracture incidence. "Peptidoglycan recognition protein 1 (PGLYRP1) is a crucial mRNA in osteoporosis, a condition characterized by the dysregulation of innate immunity and bacteriostatic activity." (PMID 41158629, 2025). "PGLYRP1 and SLC11A1 may influence the advancement of osteoporosis by regulating various biological processes." (PMID 41158629, 2025).
pancreatic cancer (1 paper, 2024). "Not only is PGLYRP1 a novel CSC marker, but it promotes immune evasive properties, plays a pivotal role in initiating pancreatic cancer and facilitates metastatic colonisation." (PMID 38754953, 2024).
pancreatitis (1 paper, 2024). Inflammation of the pancreas. "In histological sections of the healthy pancreas, we could not detect PGLYRP1 expression in epithelial cells, although in pancreatitis, some acini presented PGLYRP1." (PMID 38754953, 2024).
pneumococcal pneumonia (1 paper, 2016). A febrile disease caused by STREPTOCOCCUS PNEUMONIAE. "We identified ERM complex, PGLYRP1, PTPRC/CD45 and POSTN as new players in the pathogenesis of pneumococcal pneumonia." (PMID 27247105, 2016).
Splenomegaly (1 paper, 2020). Abnormal increased size of the spleen. "We examined B. burgdorferi infection in mice lacking PGLYRP1 and observed an increased spirochete burden in the heart and joints, along with splenomegaly." (PMID 33175909, 2020).
Vogt-Koyanagi-Harada syndrome (1 paper, 2024).
infection (79 papers, 2007 to 2026). The state of being infected such as from the introduction of a foreign agent such as serum, vaccine, antigenic substance or organism. "Some up-regulated genes at 21 dpi (e.g., Ltf, Cxcl9, Pglyrp1, Prg2, Cxcl13, Cxcl3, Ccl9, Ccl19, Krt5, Krt14, Krt15, Krt17, and Slpi) were also identified in a previous infection study by using H1N1(PR8)." (PMID 38005876, 2023). "Bovine peptidoglycan recognition protein 1 located on chromosome 18, having 3 exons, has a significant role in regulating inflammation, response to infection, and post-infection healing." (PMID 36911690, 2023). "We confirmed this interaction using orthogonal methods and identified a role for PGLYRP1 in controlling B. burgdorferi burden during murine infection." (PMID 33175909, 2020). "In fact, host defense (antimicrobial) peptides such as CATHL6, LCN2, and PGLYRP-1 are attractive candidates for therapeutic development and represent potential alternatives to antimicrobials for infection management." (PMID 33195534, 2020). "PGLYRP1 also dampens inflammatory responses and impedes bacterial killing later in infection." (PMID 41040336, 2025). "However, the PGLYRP1-/- mice had a significantly higher spirochete burden in the hearts and joints at 25 dpi, suggesting a role for PGLYRP1 in controlling B. burgdorferi dissemination during the systemic phase of infection." (PMID 33175909, 2020).
bacterial infection (28 papers, 2004 to 2025). "For example, peptidoglycan recognition protein 1, which has amidase activity and binds to peptidoglycan in response to bacterial infection, was highly induced (at least 3.8-fold) in all four profiles (although the p value in acute secretome is 0.064)." (PMID 29121106, 2017).
tumor (28 papers, 2013 to 2026). "While PGLYRP1 overexpression is associated with PDAC tumour cells, inflammation can slightly increase its expression in acini." (PMID 38754953, 2024). "Following this idea, we investigated if PGLYRP1 expression favoured primary tumour formation and metastatic colonisation after orthotopic implantations in C57Bl/6J mice pancreata." (PMID 38754953, 2024). "PGLYRP1 overexpression increased primary tumour size and induced a more dedifferentiated phenotype as determined by histological analysis." (PMID 38754953, 2024). "Together, these data suggest that PGLYRP1 protects tumour cells, and in particular CSCs, from immune-mediated elimination." (PMID 38754953, 2024). "Pglyrp1 expression was first validated in primary KPC tumours, confirming its expression predominantly in the triple-positive population." (PMID 38754953, 2024). "To evaluate the expression of PGLYRP1 during tumour evolution, we combined immunofluorescence analyses with interrogation of single-cell RNA-seq data." (PMID 38754953, 2024). "Mechanistically, tumour necrosis factor alpha (TNFα)-regulated PGLYRP1 expression interferes with the immune tumour microenvironment (TME) landscape, promoting myeloid cell-derived immunosuppression and activated T-cell death." (PMID 38754953, 2024). "In our TMA, patients with detectable levels of PGLYRP1 in the tumour compartment presented lower infiltration of immune cells, although not significant, again probably due to the limited number of samples." (PMID 38754953, 2024). "We also confirmed PGLYRP1 expression in epithelial tumour cells across a series of tissue samples including PDXs and freshly resected tumours and its absence in healthy tumour-adjacent pancreas, with results similar to those obtained in our mouse models." (PMID 38754953, 2024). "We next explored TNFα as a potential cytotoxic mediator shaping tumour evolution and the role of PGLYRP1 in regulating/counteracting this effect." (PMID 38754953, 2024). "Although most of the patient samples expressed PGLYRP1 in the TME, a smaller fraction expressed PGLYRP1 in tumour cells." (PMID 38754953, 2024). "Previous studies have shown that deletion of PGLYRP-1 in mice resulted in reduced tumor growth accompanied by an enhanced activation/effector phenotype in CD8+ T cells." (PMID 39483916, 2024). "PGLYRP1 was initially thought to be cytotoxic by itself for tumor cells and to function similarly to Tumor Necrosis Factor-α (TNF-α); further research showed that PGLYRP1 alone does not possess cytotoxic activity." (PMID 39204415, 2024). "In KPC transformed pancreas; however, PGLYRP1 was detectable as early as 10 weeks and throughout tumour evolution." (PMID 38754953, 2024). "Risk factors, like STC1, COL5A2, COL3A1, and BGN, were significantly correlated with poor OS, while BMPR2 and PGLYRP1 were only found to be protective factors in 2 of 33 tumor types." (PMID 36479101, 2022). "Thus, PGLYRP1 expression seems to modulate the immune response during tumour formation by altering immune cell infiltration and conferring resistance to activated T cells and MΦs." (PMID 38754953, 2024). "Previous findings showed that PGLYRP1 could interact with Hsp70 to form a stable complex that was cytotoxic against some tumour cell lines and promoted apoptosis and necroptosis." (PMID 38213773, 2024). "Taken together, these results suggest that the expression of PGLYRP1 by CSCs and other tumour cells could be relevant for tumour initiation and progression." (PMID 38754953, 2024). "In summary, PDAC cells, particularly CSCs, upregulate PGLYRP1 in response to inflammatory signals, notably TNFα from both tumour and tumour microenvironment (TME) cells (eg, MΦ), as a strategy to mitigate its cytotoxic effects by blocking TNFα/TNFR1 signalling." (PMID 38754953, 2024).